VAV3 (vav guanine nucleotide exchange factor 3)
Diseases named in the same sentence as VAV3 in open-access papers (continued):
Sharing a sentence is not in itself a finding about the gene and the disease.
tumor (43 papers, 2008 to 2026). "Meanwhile, Vav3 is a signal molecule in proteoglycans in cancer that is considered an important tumor‐associated pathway and AR is enriched in oocyte meiosis, a pathway related to cell division." (PMID 38804848, 2024). "Immunohistochemical analyses of VAV3 were carried out to determine its association with therapeutic response and different tumor markers." (PMID 24886537, 2014). "In addition, Vav3 is implicated in receptor-triggered angiogenesis, and host deficiency in Vav2/Vav3 retards tumor growth based on impaired vascularization within the tumor bed." (PMID 30083818, 2018). "Exosome-mediated communication has been shown to influence metastatic behavior and immune evasion, while metabolic reprogramming through the mevalonate pathway, regulated by VAV3, supports tumor growth and distant spread." (PMID 41516402, 2026). "We found that CAV2 and VAV3 were significantly highly expressed in tumor samples, whereas the expression levels of THBS3 and FLT1 were not significantly altered in tumor samples." (PMID 36950136, 2023). "Combined with the immunohistochemical data from the database, we investigated the protein level changes of CAV2, FLT1, THBS3 and VAV3 in tumor samples and normal control samples." (PMID 36950136, 2023). "This complex increases the expression of downstream proteins, such as vav guanine nucleotide exchange factor 3/F11 receptor, and ultimately leads to tumor progression and a poorer tumor prognosis." (PMID 35465324, 2022). "Vav3 expression in gastric cancer tissues was related to tumor differentiation, tumor invasion, lymphatic metastasis, neurovascular invasion and clinicopathological stage." (PMID 32322580, 2020). "We found significant cis-eQTL of genes near NRG1, NKX2-1, DIRC3, PCNXL2 and VAV3 in the normal and tumour thyroid tissue." (PMID 28703219, 2017). "Published studies showed that mir-499a-5p is a tumor suppressor miRNA by targeting the VAV3 gene and its reduction correlate with poor clinical outcome in NSCLC." (PMID 27600084, 2016). "Our study demonstrates that VAV3 overexpression in CRC tissues is closely correlated with tumor invasion and metastasis." (PMID 25791293, 2015). "In this study, we investigated the involvement of the VAV3 oncogene in tumor progression and in the prognosis of human CRC." (PMID 25791293, 2015). "Tumors from mice treated with si-Vav3 plus docetaxel were statistically smaller than those from mice treated with docetaxel alone (P < 0.01), and the tumor volume on day 70 was 59% smaller than that when treatment was initiated." (PMID 23566222, 2013). "The knockout mice had a 2-fold reduction in total tumors, indicating that the knocked out genes (Vav2 and Vav3), were important to tumor formation." (PMID 23935452, 2013). "On day 70 after inoculation, tumor tissues were harvested from euthanized mice and subjected to immunoblot analysis of Vav3, H&E staining and immunohistochemical staining of Vav3, Ki-67, pAR, and a commercially available cell death marker, M30 CytoDeath." (PMID 23566222, 2013). "Despite the large number of Rho GEFs present in both normal and tumoral epidermis, we demonstrate that the co-expression of the exchange factors Vav2 and Vav3 is critical for the development of this tumor type." (PMID 23935450, 2013). "Vav2−/−;Vav3−/− FVB mice also displayed lower kinetics of tumor development, a 2-fold reduction in tumor burden per mouse, and a decrease in the percentage of cSCC development when subjected to the complete DMBA/DMBA tumorigenic method." (PMID 23935450, 2013). "It is likely that these second-level signaling defects also contribute to the lower tumor burden observed in Vav2−/−;Vav3−/− animals, since previous reports have shown that IL6-mediated signaling is essential for skin tumorigenesis." (PMID 23935450, 2013).
tumor (continued). "Xenograft tumor growth was slightly inhibited by si-Vav3/atelocollagen complex injection and combined use of si-Vav3/atelocollagen complex and docetaxel produced a greater effect than docetaxel alone." (PMID 23566222, 2013). "The effects of si-Vav3/atelocollagen complex alone or in combination with docetaxel were assessed on xenografts in nude mice by tumor growth delay." (PMID 23566222, 2013). "For mice treated with si-Vav3, the tumor volumes were 5-fold greater and the size of tumors on day 70 were statistically smaller than those of tumors from mice treated with the vehicle control (P < 0.01)." (PMID 23566222, 2013). "We further revealed that tumor cell hypoxia induced Vav3 overexpression with androgen-independent growth and malignant behavior in LNCaP cells." (PMID 23566222, 2013). "Among the tumor sections, Vav3 staining was found in approximately 67% (27/35) of the specimens with well to moderately differentiated tumors and 100% (8/8) of those with poorly differentiated tumors, respectively." (PMID 18518979, 2008). "Given the structural similarity and overlapping functions of VAV proteins, it is plausible that VAV3 may also play tumor suppressor roles akin to VAV1." (PMID 39200159, 2024). "Furthermore, elevated VAV3 expression was associated with increased infiltration of B cells, macrophages, and neutrophils into the RCC tumor microenvironment." (PMID 39200159, 2024). "MSC-derived exosomes loaded with miR-499a-5p could suppress tumor growth migration, invasion, or angiogenesis of EC cells by targeting VAV3, which is a guanine nucleotide exchange factor (GEF) that regulates the activity of Rho/Rac family GTPases." (PMID 39188680, 2024). "In the Vav family, Vav3 plays a critical role in tumor development and metastasis." (PMID 37591108, 2023). "Highly expressed VAV3 can promote tumor cell growth, metastasis, and drug resistance." (PMID 35392234, 2022). "Importantly, Vav3 can induce cell transformation and targeted overexpression of Vav3 in prostatic epithelium induces tumor formation in mice." (PMID 30083818, 2018). "By contrast, the Vav2/Vav3-dependent gene signature was found conserved in fully developed tumors, indicating that it may also play roles in tumor maintenance and/or progression." (PMID 23935452, 2013). "The team also showed that TPA has a different effect on wild-type and knockout mice; knockouts do not have the normal proliferative and inflammatory responses to the chemical, indicating that Vav2 and Vav3 are needed for these responses and subsequent tumor formation." (PMID 23935452, 2013). "Interestingly, we observed EGF-induced alternative promoter usage of genes that have previously been implicated in tumor progression (e.g., VEGFC, PTK2, IL18 and VAV3) or in cell survival/proliferation (e.g., FBXW7, BID, ABL2)." (PMID 24324612, 2013). "Additionally, as VAV3 plays a role in immune signaling modulation within the tumor microenvironment, its expression may also influence response to immunotherapies, a hypothesis warranting further investigation." (PMID 40496857, 2025). "Despite this relevant difference, VAV proteins share a very similar structure and can exhibit overlapping functions, suggesting that VAV2 and VAV3 might play tumor suppressor roles similar to those carried out by VAV1 beyond the long-held signaling archetype for RHO GEFs." (PMID 34571765, 2021). "miR-499-5p may also act as a tumor suppressor gene via the targeting of VAV3." (PMID 30719033, 2018). "In addition, we discovered great concordance of Vav3 (covering both full-length Vav3 alpha and 5′-truncated Vav3.1) and Vav3.1 transcript levels in individual patients, suggesting that overexpression of Vav3 in tumor tissue is mainly due to Vav3.1, similarly as in OC." (PMID 30083818, 2018). "This study also investigated the involvement of VAV3 in the growth and spread of LoVo CRC cells and in vivo tumor growth in nude mice by using shRNA technology to specifically knock down VAV3." (PMID 25791293, 2015).
tumor (continued). "Among them, VAV3 is the member of the VAV family of Rho GTPas nucleotide exchange factors, and it reportedly has been involved in tumor progression and metastasis." (PMID 25360158, 2014). "Up-regulation of VAV3 and TWIST1 oncogenes and repression of the DKK3 tumor-suppressor was observed in PC346DCC, suggesting a potential AR bypass mechanism." (PMID 20976069, 2010). "This is in agreement with previous studies indicating that the combined elimination of Vav2 and Vav3 does not elicit any overt epidermal or skin defects in mice." (PMID 35534539, 2022). "An important issue to be further addressed in the near future is to verify the relevance of the VAV1-dependent tumor suppressor function in VAV2- and VAV3-driven tumors, particularly in those that may be NOTCH1-dependent." (PMID 34571765, 2021). "(iii) The inverse correlation found between the abundance of the NR2F1 mRNA and the transcripts for other signaling elements of the pathway under analysis in this work (VAV2, VAV3, and CDH1) in human tumor samples according to in silico coexpression matrix analyses." (PMID 30087437, 2019). "The lower tumor burden observed in DMBA/DMBA-treated Vav2−/−;Vav3−/− mice indicated that Vav proteins may have direct roles during the initiation phase of CSTs." (PMID 23935450, 2013). "This phenotype is specifically driven by the deficiency in this Vav family member, because we have not observed statistically significant increases in deaths/tumor rates in Vav2–/–, Vav3–/– or Vav2–/–;Vav3–/– mice when compared to control littermates." (PMID 20011522, 2009). "In contrast, Vav3 staining, detected in both cytoplasm and nucleus of the epithelial cells but not in stroma of breast tissues, was found in 35 out of 43 tumor tissue sections (35/43, 81%, p < 0.0001)." (PMID 18518979, 2008). "However, expression of Vav3/Vav3.1 did not change with FIGO stage, and there was no appreciable association with tumor grade." (PMID 30083818, 2018). "Five of the GEFs described to promote GB cell motility, including Ect2, Vav3, Trio, SGEF, and SWAP-70, are overexpressed in GB versus non-neoplastic brain, and Dock180 expression is higher in the tumor rim than in the tumor core." (PMID 24109588, 2013).
cancer (39 papers, 2009 to 2026). A tumor composed of atypical neoplastic, often pleomorphic cells that invade other tissues. "In the clinical setting, Vav3 is associated with cancer progression and recurrence and furthermore mediates resistance to certain treatments, such as breast cancer endocrine therapy." (PMID 30083818, 2018). "The rs17019888 variant may influence RCC progression by modulating VAV3 expression and affecting cancer-related pathways and immune cell infiltration." (PMID 39200159, 2024). "Furthermore, several GEFs including PREX1 and Vav2 as well as Vav3 are reported to be over-expressed and associated with carcinoma progression." (PMID 29454349, 2018). "Carcinomas from Vav2;Vav3-deficient mice also displayed up-regulation of the Hgf mRNA." (PMID 23935450, 2013). "VAV3 facilitates ERBB4-mediated cancer cell migration, linking growth factor signaling to enhanced motility and invasion." (PMID 41516402, 2026). "Another protein, VAV3, has been identified as a critical player in the modulation of immune responses and cancer cell behavior." (PMID 40310419, 2025). "As a GTPase regulator, VAV3 activates the Rho GTPase family in cancer and in the vascular endothelial barrier, and is potentially associated with metabolic syndrome and obesity 16-20." (PMID 38617550, 2024). "Previous results have shown that VAV3 activity plays important tumorigenic functions in a number of cancer models." (PMID 35650206, 2022). "VAV3 (Vav guanine nucleotide exchange factor 3) counteracts apoptosis and is overexpressed in various cancers." (PMID 35486664, 2022). "Previous studies have shown an involvement of Vav3 in the migration of vascular smooth muscle cells, the granule cells of the cerebellum and in cancer cell migration." (PMID 36531963, 2022). "Several studies have also shown that Vav3 is activated by the tyrosine kinase EphA2 receptor to activate Rac and thus, increase cancer cell migration and proliferation." (PMID 32322580, 2020). "Of note, overexpression of Vav3/Vav3.1 was equally pronounced in type 1 (endometrioid) and type 2 (serous/clear cell) cancers, indicating a common mechanism of Vav3 activation among principal EC sub-entities." (PMID 30083818, 2018). "We found several cellular growths or cancer-related pathways that were associated with SNPs of NRG1, VAV3, DIRC3, SEPT11 and INSR." (PMID 28703219, 2017). "Like Vav1, Vav2 and Vav3 become oncogenic following N-terminal truncation, yet there appears to be Vav isoform-distinct functions in cancer." (PMID 26353933, 2015). "We first tested the anti-cancer potential of interrupting the Vav3 signaling pathway using siRNA followed by investigating the impact of si-Vav3 in combination with docetaxel." (PMID 23566222, 2013). "Collectively, these results indicate that the PI3K/Akt signaling pathway plays a crucial role in LNCaPH cell growth, although cancer cell growth regulated by Vav3, at least in part, originated from activated ERK signaling." (PMID 23566222, 2013). "Finally, we investigated whether the tumors that developed in Vav2;Vav3-deficient mice could be the result of the outgrowth of cancer cells that, due to selection events, could have compensated the lack of Vav proteins by the exacerbation of other signaling routes." (PMID 23935450, 2013). "Based on the present study, it could be noted that over-expression of VAV3 and CASC4 genes in PLW gilts during early pregnancy was related to the regulation of Rho/Rac family GTPases and cancer susceptibility activities." (PMID 32429378, 2020). "Also, high levels of Vav3 have been observed in various types of cancers, including glioblastoma, prostate cancer and colorectal cancer." (PMID 26353933, 2015). "However, the effect of si-Vav3 was weak and this study was designed to determine the combinatorial effects of docetaxel on cancer cell growth and apoptosis." (PMID 23566222, 2013). "Unlike the case of VAV1, there are no consistent examples of mutations for the VAV3 gene in cancer." (PMID 34571765, 2021).
cancer (continued). "Therefore, Vav3 overexpression may contribute to androgen receptor (AR) signaling through the PI3K-Akt pathway to stimulate cancer cell growth." (PMID 32322580, 2020). "Hence, Vav3 constitutes an established marker for cancer with prognostic and predictive significance, and accumulating evidence suggests a causal role in tumorigenesis that might be therapeutically exploitable." (PMID 30083818, 2018). "However, the roles and underlying mechanisms of VAV3 overexpression in cancer cell growth and spreading are not well understood." (PMID 25791293, 2015). "VAV3 interferes with multiple biological mechanisms such as proliferation, invasion, migration, cell cycle control, epithelial–mesenchymal transition (EMT), and apoptosis, which in turn facilitates cancer progression." (PMID 40332226, 2025). "Moreover, LEF1, RUNX2, CSF1R, VAV3, and FZD3 have been reported to take part in the development of cancer." (PMID 35340229, 2022). "Hitherto, don’t have been reported that the DNMT3B binding in promoters results in an increased gene expression if not quite the opposite, hence, we focus on four downregulated genes with cis elements and functionally related to cancer, PPL1, IRF1, BRAF, and VAV3." (PMID 36460706, 2022). "Although the mechanism responsible for VAV3 involvement in gemcitabine and AraC response is unclear, given the multiple roles of VAV3 in cancer development, it was not surprising that this gene might contribute to variation in response to chemotherapeutic agents." (PMID 19898621, 2009).
infection (7 papers, 2011 to 2025). The state of being infected such as from the introduction of a foreign agent such as serum, vaccine, antigenic substance or organism. "For gene candidates, Vav3, Ptpn22, FcgR1 and S100a10, qPCR corroborated up-regulated expression found in susceptible AKR on day 35 post infection." (PMID 23442222, 2013). "Vav1 and 2 mRNA and protein and Vav3 mRNA were present in MDMs but were not affected by DENV-infection." (PMID 38054722, 2024). "Of those tested Cdc42ep3 (CDC42 effector protein), ARHGDIB (Rho GDP dissociation inhibitor (GDI) beta), Acta2 (Alpha actin 2), Egr2 (Early growth response 2), IL-6 (Interleukin 6) and Vav3 (vav 1 guanine nucleotide exchange factor), were induced by EPEC infection but not by infection with EPEC Δtir." (PMID 21490959, 2011).
VAV3 also shares sentences with these, for which no sentence is quoted: Alzheimer’s dementia (2 papers); Arthritis (2); dysplasia (2); lymphoma (2); acute myeloid leukemia (1); adenocarcinoma (1); allergic rhinitis (1); Alzheimer's disease (1); ankylosing spondylitis (1); artery thrombosis (1); asthma (1); autoimmune disease (1); brain tumours (1); cardiovascular disease (1); Chronic colitis (1); copy number variation (1); cystic fibrosis (1); developmental delay (1); diffuse large B-cell lymphoma (1); dilated cardiomyopathy (1); fibrosis (1); follicular lymphoma (1); fungal infections (1); Hashimoto thyroiditis (1); head and neck squamous cell carcinoma (1); head and neck tumours (1); inflammatory bowel disease (1); intestinal disease (1); Kidney Clear Cell Carcinoma (1); kidney damage (1).
A further 17 diseases each share a sentence with VAV3 in 1 paper.